IL6 (interleukin 6)
Diseases named in the same sentence as IL6 in open-access papers (continued):
Sharing a sentence is not in itself a finding about the gene and the disease.
depression (continued). "After adjusting for potential confounders, such as BMI and smoking, and correcting for multiple testing, four proteins remained significantly associated with depression: fibroblast growth factor 21 (FGF21), FGF19, Interleukin-6 (IL-6) and Interleukin-20 receptor subunit alpha (IL-20RA)." (PMID 39523673, 2024). "Further evidence supporting the hypothesis that inflammation is a cause rather than a consequence of depression is provided by a Mendelian randomization analysis of a UK Biobank sample, demonstrating that IL-6 and CRP are causally linked with depression." (PMID 37848651, 2024). "Based on these studies, there is preliminary evidence that YBIs may be associated with increased serum brain-derived neurotrophic factor (BDNF) and reduced serum cortisol and interleukin-6 (IL-6) in patients with depression." (PMID 38928543, 2024). "Importantly, increasing the expression of hsa-miR-532-5p in these mice led to a decrease in depression-like behaviors and the suppression of inflammatory markers like IL-6, IL-1β, TNF-α, and MCP-1." (PMID 39451524, 2024). "A large cohort study among British civil servants (a general population or with MDD not specified) showed that higher serum levels of IL-6 at baseline were associated with subsequent cognitive symptoms of depression in both sexes at follow-up." (PMID 39358787, 2024). "Research might progress on this, considering high levels of cortisol and IL-6 may predict depression onset." (PMID 39839132, 2024). "Focusing on activity/bioavailability of IL-6 could help us better understand how IL-6 contributes to depression and may aid the development of strategies for precise therapeutic targeting of the IL-6 pathway in depression." (PMID 38442505, 2024). "IL-6 activates the metabolic enzyme indoleamine 2,3-dioxygenase and significantly reduces synthesis of 5-HT, indicating that inflammatory cytokines play an important role in brain regions closely related to depression and 5-HT conversion." (PMID 39135980, 2024). "Alteration in inflammatory markers such as IL-6, psychological factors such as stress and depression, or circadian rhythm can be the consequences of these differences that may lead to disruption in sleep." (PMID 38310318, 2024). "A weak causal relationship was established with a prospective study involving 400 Taiwanese patients indicating that statin-treated patients produced less IL-6 and had lower rates of depression, supporting an inflammatory hypothesis for depression." (PMID 38304427, 2024). "IL-6 KO mice have not been evaluated in chronic stress paradigms; however, IL-6-deficient mice are resilient to the development of depression-like behaviors in the learned helplessness paradigm." (PMID 38791125, 2024). "Also, by reducing IL-1α, IL-6, and TNF-α expression and suppressing NF-κB activity in the hippocampus, Lacticaseibacillus paracasei NK112 protected against depression caused by Escherichia coli." (PMID 39459643, 2024). "In contrast, a recent study that focused on a more homogeneous sample of patients with recent depression did not observe significant elevations in CSF IL-6 levels nor associations with the severity of depressive symptoms." (PMID 38336728, 2024). "This evidence implicates inflammation in the aetiology of depression, suggesting that IL-6 could be a mechagnostic (mechanism-related) and theragnostic (treatment-response related) marker of depression." (PMID 38442505, 2024). "The mechanisms underlying anxiety and depression following TBI are currently unclear, but inflammation post-TBI is speculated to be a contributing factor, associated with elevated levels of TNF-α, IL-6, IFN-α, and CRP." (PMID 39554848, 2024). "Additionally, PAMK decreased anxiety/depression-like behaviors and expression of IL-6, IL-1β, TNF-α, and MCP-1 in the hippocampus." (PMID 39599623, 2024). "Serum IL-6 levels were higher in AD patients than depression patients." (PMID 38247923, 2024).
depression (continued). "We also found significant evidence of differential effects by depression and pro-inflammatory cytokines such as IL-1β, IL-6 and TNF-α, in which the effects of D-50 (vs. placebo) were significantly greater among those with depression or elevated plasma concentrations of such cytokines." (PMID 39019875, 2024). "Likewise, in a model of depression induced by corticosterone, an increase in serum levels of IL-6 and IL-1β was found, indicating that inflammatory processes are involved in the development of depressive disorders." (PMID 39585071, 2024). "Furthermore, the dysregulation of serum inflammatory cytokines, such as IL-1β, IL-6, and TNF-α, has been observed in pediatric patients with major depressive disorder (MDD), and it is linked to depression in children with cancer." (PMID 38927907, 2024). "While a negative study for Brain FADE, at least this study provides definite causal evidence for the lack of involvement of IL-6 in fatigue and depression in this type of MS." (PMID 38304427, 2024). "This biomarker shows robust associations with several clinical (i.e., somatic symptoms, fatigue, depression severity, quality of life) and cognitive (i.e., psychomotor speed) outcomes and performs well in comparison to single inflammatory proteins, like IL-6, CRP, and sIL-6R." (PMID 38442505, 2024). "The cytokine IL-6 negatively affects PV neurons, so, unsurprisingly, both cortical PV and peripheral levels of IL-6 correlate with learned helplessness behavior in maternally separated rats, further supporting their role in depression." (PMID 38672480, 2024). "Regarding the statistically significant correlation between HDRS and measured parameters, reducing HDRS and relieving depression symptoms might lead to a reduction in IL-6, STAT3, NLRP3, and an elevation in AMPK." (PMID 38855751, 2024). "Additionally, chronic mild stress and other depression models have shown increased levels of pro-inflammatory cytokines like IL-1β, IL-6, TNF-α, and IL-17 in both animals and humans." (PMID 39335629, 2024). "Given that neuroinflammation is an important factor in the pathophysiology of anxiety and depression, the effect of the probiotic treatment could be attributed to a reduction in serum proinflammatory cytokines such as IL-6." (PMID 38399815, 2024). "It has been suggested that there may be some kind of feed-forward regulation in depression, with IL-6 driving IL-10 release and thereby suppressing the inflammatory response." (PMID 39882160, 2024). "Similar to TNFα, IL-6 has long been investigated in relation to the pathophysiology of depression." (PMID 39358787, 2024). "Research on IL-6 is the most extensive due to its higher significance in depression." (PMID 39329797, 2024). "This novel measure of IL-6 activity/bioavailability may provide further insight into the biological mechanisms contributing to cognitive dysfunction in depression, aiding future treatment development." (PMID 38442505, 2024). "Furthermore, it leads to heightened corticosterone levels and triggers activation of the innate immune system, resulting in elevated inflammatory cytokines (such as IL-6, IL-1β, and TNFα), thus impacting the onset of depression." (PMID 38680928, 2024). "Remarkably, selective dorsal vagotomy prevented the onset of depression-like behaviors, rise in plasmatic IL-6 levels, and decline in synaptic proteins in the prefrontal cortex following oral introduction of Lactobacillus intestinalis and Lactobacillus reuteri." (PMID 38523835, 2024). "IL-6 may cross the blood–brain barrier, suggesting its possible involvement in neuroinflammation and participation in the pathogenesis of depression and schizophrenia." (PMID 38248262, 2024). "Interestingly, the strongest link between depression, inflammation and statins is via the interleukin 6 (IL-6) pathway." (PMID 38304427, 2024). "In a meta-analysis IL-6, IL-8 and TNf-α were elevated in the CSF of individuals with depression." (PMID 39526037, 2024).
depression (continued). "In addition, there is a certain correlation between depression and serum inflammatory factors such as IL-6, TNF-α, and CRP." (PMID 38698338, 2024). "Indeed, recent meta-analyses have reported higher levels of TNF-α, CRP, and IL-6 levels in adolescents with depressive disorders when compared with control individuals." (PMID 38824135, 2024). "Considering the results of our study, we hypothesize that IL-6 increased level may be involved in the observed depressive disorders that accompany disk degeneration." (PMID 38646609, 2024). "Another anti-IL-6 antibody worth mentioning when talking about treating depression is tocilizumab, whose function is to inhibit the activation of both membrane-bound and trans-receptor signaling, as described in two published studies that confirmed its positive effect on symptoms related to MDD." (PMID 39273641, 2024). "Therefore, future studies should focus on the association of IL-6 with BDNF and brain activity of serotonin and IDO to understand the role of neuro-inflammation in the causation of depression in GDM." (PMID 37365247, 2023). "The polymorphic variants of IL6, IL18, and TNFA were associated with depression and SCZ." (PMID 37510364, 2023). "Plausibly, increased CRP and fibrinogen predicted heightened depression components, particularly somatic symptoms, by producing more proinflammatory cytokines from peripheral blood mononuclear cells (e.g. IL-6, tumor necrosis factor-α) (Haroon, Raison, & Miller, 2012)." (PMID 35924730, 2023). "Regarding the beneficial effect of an IL-6 antagonist (i.e., tocilizumab), a large multicenter study found that weekly injections of tocilizumab over 24 weeks had a favorable effect in decreasing anxiety and depression levels." (PMID 37346903, 2023). "Previous research has indicated that depression is accompanied by increased levels of inflammatory markers, such as C-reactive protein (CRP) and interleukin-6, which could be particularly relevant for treatment-resistant depression." (PMID 37904091, 2023). "This may explain why Tat tended to decrease PFC IL-6 and IFN-γ levels, which are implicated in depression, even though Tat(+) and morphine co-exposed mice exhibited greater depressive-like behavior overall than control mice." (PMID 36992299, 2023). "IL-6, TNF-α and IL-1, and their association to depression could be linked to their ability to trigger the activation of HPA axis." (PMID 36911685, 2023). "The development of depression is often accompanied by an increased inflammatory response, which increases levels of peripheral and central pro-inflammatory cytokines, including interleukin-1β (IL-1β), interleukin-6 (IL-6), and tumor necrosis factor-α (TNF-α)." (PMID 38094892, 2023). "The normalization of IL-6 relieves the symptoms of depression." (PMID 37894116, 2023). "Elevated levels of inflammatory factors such as C-reactive protein (CRP) and interleukin 6 (IL-6) may promote the development of depression." (PMID 37032915, 2023). "This hypothesis is endorsed by prior data suggesting that DFD might be considered a continuous stressor modulating the expression of IL-6, which is influenced by a genetic polymorphism that contributes to TMD and depression, impacting the QoL." (PMID 37471347, 2023). "The combined therapy could reduce The depression state and the levels of IL-6 and TNF-α, and enhance the cognitive function of patients." (PMID 37273720, 2023). "Tumor necrosis factor α (TNF-α) and Interleukin 6 (IL-6) can attach to their receptors and trigger cerebral Nuclear factor kappa B (NF-kB) signaling, which can upregulate the production of secondary cytokines, and finally induce depression symptoms." (PMID 37386551, 2023). "In bipolar depression, IL-6 seems to be the predominant cytokine, IL-4 dominates in the euthymic state, and IL-2, IL-4, and IL-6 are prevalent in the manic state, while patients with unipolar depression mainly have elevated TNF-α, IL-6, and sIL-2R." (PMID 37510730, 2023).
depression (continued). "Although TNF-α, IL-6, and IL-1β play crucial roles as acute phase proteins, they may act differently in the pathology of depression." (PMID 37009013, 2023). "Previous studies have reported that patients with kidney disease have higher levels of interleukin-6 (IL-6) and C-reactive protein, which are both considered to be related to the severity of depression due to increased production through various pro-inflammatory pathways and decreased clearance." (PMID 37006563, 2023). "Electroacupuncture can downregulate inflammatory factors such as IL-6 in the hippocampus of depressed rats, suggesting that electroacupuncture may relieve depression through immune regulation." (PMID 38053532, 2023). "These markers include CRP and IL-6; the study concluded that depression and anxiety in RA patients were driven by the same immune-inflammatory pathway which is part of the pathophysiology of RA disease itself, and not driven by the experience and burden of the disease." (PMID 37346903, 2023). "Additionally, IL-6, a pro-inflammatory cytokine, is increased in depression because of neuroinflammatory processes." (PMID 36986859, 2023). "Finally, the vast majority of research that has examined the associations between insomnia, inflammation, and depression, has assessed CRP and circulating levels of IL-6 and TNF." (PMID 36879913, 2023). "Despite the lack of comprehensive research on the relationship between IL-6 levels and amygdala emotional reactivity in the context of depression/anxiety, several seminal studies have investigated the relationship between IL-6 levels and amygdala emotional reactivity in general." (PMID 37324818, 2023). "Patients with higher serum preoperative IL-6 levels tended to experience more severe depression." (PMID 37324195, 2023). "It has been stated earlier that elevated IL-6 activity may lead to depression through stimulation of hypothalamic–pituitary–adrenal axis or by influencing the metabolism of neurotransmitters." (PMID 37365247, 2023). "Therefore, neuroinflammation has gained increasing attention and is regarded as a key role in depression; IL-6, IFN-α, and C-reactive protein (CRP) have been shown to be linked to depression." (PMID 37630578, 2023). "Serum IL-6, IL-8, IL-18, and IFN-γ levels are estimated biomarkers for depression severity in nurses, showing that they may increase the risk of inflammatory dysregulation when nurses have high depressive symptoms." (PMID 37637801, 2023). "At the cellular level, repercussions of these processes could be the production of IL-1α, IL-1β, TNF-α, and IL-6, as well as the activation of microglia and the impairment of astrocytes in depression." (PMID 36899845, 2023). "Treatment-resistant depression patients showed a simultaneous increase in cortisol and IL-6 levels, as well as a high correlation between a decrease in the expression of the glucocorticoid receptor (GRa) and the upregulation of the inflammatory genes in monocytes." (PMID 38067176, 2023). "Furthermore, the antidepressant effects of MLT were found to be related to the modulation of neuroinflammation by regulating hippocampal NF-κB phosphorylation and cytokines (TNFα, IL-1β, and IL-6) in the LPS-induced depression model." (PMID 36747075, 2023). "Indeed, previous studies have shown that concentrations of inflammatory markers such as C-reactive protein and interleukin-6 correlate with the scores of depression and anxiety, supporting our findings." (PMID 37138731, 2023). "And in terms of peripheral and central inflammation, some studies have suggested that ECT in patients with depression activates peripheral blood mononuclear cells in 30 min, increases circulating pro-inflammatory factors such as IL-1β and IL-6 at 3 h, and falls back to baseline at 24 h." (PMID 36624089, 2023). "Furthermore, higher levels of IL-6 predicted over time the chronicity of depression, as well as higher severity of depression at follow-up." (PMID 35761500, 2023).
depression (continued). "Moreover, decreased IL-6 and TNF-α levels are associated with hippocampal size and antidepressant efficacy, highlighting the role of neuro-inflammation in depression and psychiatric disease." (PMID 37699900, 2023). "This review finds that alterations in concentrations of certain biomarkers of neuroinflammation (interleukin-6, tumour necrosis factor-α, neopterin) may influence the association between HIV and depression." (PMID 37693812, 2023). "Our results do not show a deniable association between immune system activity and MDD, thus, it is plausible that other inflammatory profiles, besides CRP, IL-6 and TNF, may be associated with different depression subtypes." (PMID 36966195, 2023). "Subsequently, anxiety- and depression-like behaviors and spatial learning and memory function were evaluated in the offspring, as were the hippocampal levels of markers of inflammation (IL-1β, IL-6, TNF-α) and synaptic function (PSD-95, SYN)." (PMID 37560531, 2023). "The current study suggested that both TNF-α (-308G/A) and HHV-6 might affect TNF-α, IL-6, and IL-10 expression, influencing the severity and progression of depression via inflammatory processes." (PMID 37766304, 2023). "In addition, IL-6 can inhibit hippocampal neurogenesis in depression by acting on IL-6 receptors or a transmembrane protein, gp130, in the dentate gyrus or by stimulating the hypothalamic–pituitary–adrenal (HPA) axis." (PMID 37828513, 2023). "Persistent increase in IL-6 has been reported in stress reactions and in patients with depression." (PMID 37365247, 2023). "Likewise, the most repeatedly validated biomarkers of depression include hypercortisolemia, hypocholesterolemia, reduced brain-derived neurotrophic factor, and increased interleukin 6 (Caruncho and Rivera-Baltanás, 2010)." (PMID 37645061, 2023). "Patients with depression exhibit an increased expression of proinflammatory cytokines and their receptors in the peripheral blood and cerebrospinal fluid (CSF), especially IL-1β, IL-6 and TNF-α, as the cardinal feature of the inflammatory responses." (PMID 36838809, 2023). "Given the epidemiological associations identified between IL-6, tumor necrosis factor (TNF)-α, and subsequent depression, the levels of these pro-inflammatory cytokines have also been studied as potential moderators of the depressed mood response to endotoxins." (PMID 37509542, 2023). "Notably, IL-6, a proinflammatory cytokine of previous interest in depression research, showed only a minor increase at T1 (+4%)." (PMID 37881534, 2023). "The outcome measures were plasma IL-6 and IL-1β concentrations and a questionnaire including the Pittsburgh Sleep Quality Index, the Center for Epidemiology Research Depression Scale, the Somatic Symptoms Inventory, the Perceived Stress Scale, and the Holistic Body–Mind–Spirit Well-Being Scale." (PMID 37509542, 2023). "However, it seems unlikely that serum CRP and serum IL-6 should have major different effects on anxiety and depression symptoms in this group compared with other populations." (PMID 37217205, 2023). "We can cautiously claim that DIO1 and DIO3 and pivotal cytokines, mainly IL-1β and IL-6, may play a role in depression diagnosis, and further studies are suggested to explain the exact role of these molecules in larger samples with more precise methods." (PMID 37834806, 2023). "In this context, NF-κB has been hypothesized to stimulate the release of inflammatory mediators, including TNF-α, interleukin (IL)-1β, and IL-6, as well as promoting neuroinflammatory processes, finally leading to depression." (PMID 37998350, 2023). "Clinical studies have found that compared with normal people, patients with depression have proinflammatory cytokines such as tumor necrosis factor-α(TNF-α)、Interleukin-1β(IL-1β)、IL-6 and interferon While anti-inflammatory cytokines such as IL-10, IL-4, IL-8 and transforming growth factor." (PMID 37167313, 2023).